MIR3120 (microRNA 3120)
Synonyms: hsa-mir-3120; mir-3120
Gene: MicroRNA gene on chromosome 1 (172,138,808 to 172,138,888, forward strand). Ensembl gene ENSG00000283152.
Gene Ontology:
Biological process: miRNA-mediated post-transcriptional gene silencing
Cellular component: RISC complex
Homologues: Paralogues in human: MIR214 (74% identical).